TSPEAR (thrombospondin type laminin G domain and EAR repeats)
Description:
Plays a critical role in tooth and hair follicle morphogenesis through regulation of the Notch signaling pathway. May play a role in development or function of the auditory system.
Synonyms: TSP-EAR; C21orf29; MGC11251; DFNB98; ECTD14; STHAG10
Tractability: Antibody: UniProt places it where antibodies can reach, with medium confidence; UniProt predicts a signal peptide or a membrane-spanning region; its Gene Ontology location is reachable by antibodies, with medium confidence.
Gene: Protein-coding gene on chromosome 21 (44,497,893 to 44,711,873, reverse strand). Ensembl gene ENSG00000175894.
Subcellular location: Secreted; Cell surface; Cell projection, stereocilium
Gene Ontology:
Biological process: regulation of Notch signaling pathway; sensory perception of sound; tooth mineralization; signal transduction
Cellular component: cell surface; extracellular region; stereocilium; ciliary membrane
Genetic constraint (gnomAD): Loss-of-function variants: 69 observed, 72.64 expected, observed/expected ratio (o/e) 0.95, 90% interval 0.78 to 1.16. The upper end of that interval is the gene's LOEUF score, 1.16, which puts it in group 5 of 6, group 1 being the genes least tolerant of losing a copy. Missense variants: 971 observed, 910 expected, observed/expected ratio (o/e) 1.07, 90% interval 1.01 to 1.12. Synonymous variants: 402 observed, 392.18 expected, observed/expected ratio (o/e) 1.02, 90% interval 0.94 to 1.11.
Gene-disease validity (ClinGen):
ClinGen rates the evidence that TSPEAR causes each of these diseases.
nonsyndromic genetic hearing loss (autosomal recessive): Disputed.
Homologues: Orthologues: chimpanzee TSPEAR (99% identical), macaque TSPEAR (97% identical), dog TSPEAR (83% identical), pig TSPEAR (83% identical), mouse Tspear (82% identical), rat Tspear (82% identical), guinea pig TSPEAR (80% identical), rabbit TSPEAR (70% identical), tropical clawed frog tspear (62% identical), zebrafish tspearb (57% identical), zebrafish tspeara (55% identical), Drosophila melanogaster clos (23% identical).
Diseases named in the same sentence as TSPEAR in open-access papers:
TSPEAR is named in the same sentence as 15 diseases in open-access papers, as found by Europe PMC text mining. Sharing a sentence is not in itself a finding about the gene and the disease. The quoted sentences say what the papers report.
deafness (2 papers, 2014). An inherited or acquired condition characterized by the complete loss of the ability to hear from one or both ears. "Segdups, defined as regions with > 95% homology, are features that are causally implicated in recurrent CNVs mediated by NAHR and were identified in seven deafness genes: TSPEAR (4 segdups), OTOA, STRC, MYO3A, ESPN, OTOGL, CACNA1D." (PMID 24963352, 2014).
epilepsy (2 papers, 2021 to 2025). A brain disorder characterized by episodes of abnormally increased neuronal discharge resulting in transient episodes of sensory or motor neurological dysfunction, or psychic dysfunction. "Among these, variants in TSPEAR (Thrombospondin-type laminin G domain and epilepsy-associated repeats) have been implicated in autosomal recessive ED type 14 (OMIM 618180), predominantly manifesting with dental anomalies and hair dysplasia." (PMID 40428341, 2025). "Seven epilepsy-associated repeats (EARs) of TSPEAR are predicted to form a beta-propeller structure, function as part of a ligand-binding domain and mediate protein–protein interactions." (PMID 34795337, 2021).
hypotrichosis (2 papers, 2022 to 2026). A congenital condition, usually due to genetic aberrations, that is characterized by a lack of hair growth on the head and/or body. "Some features were shared with patients from Middle Eastern origin, e.g., scalp hypotrichosis, which was more prominent on the anterior of the scalp in six of our ten reported TSPEAR-ED patients, has similarly been reported in three Palestinian patients." (PMID 35741818, 2022).
Oligodontia (2 papers, 2016 to 2025). The absence of six or more teeth from the normal series by a failure to develop. "Pathogenic variants in TSPEAR have been associated with a phenotype characterized by oligodontia, nail dystrophy, and sparse hair, often accompanied by additional dermatological manifestations, reduced sweating, and craniofacial abnormalities." (PMID 40428341, 2025).
Cognitive impairment (1 paper, 2025). Abnormal cognition is characterized by deficits in thinking, reasoning, or remembering. "The absence of evident intellectual or cognitive impairment in affected individuals further supports the notion that TSPEAR-related ED primarily affects ectodermal structures, distinguishing it from syndromic forms with neurodevelopmental involvement." (PMID 40428341, 2025).
gastric cancer (1 paper, 2024). A primary or metastatic malignant neoplasm involving the stomach. "Mutation and splicing of TSPEAR can participate in the development and progression of cancers, including gastric cancer and liver cancer." (PMID 38213725, 2024). "Previous studies have shown that TSPEAR mutations are involved in the development and progression of gastric cancer and liver cancer." (PMID 38213725, 2024).
TSPEAR also shares sentences with these, for which no sentence is quoted: Ectodermal Dysplasia (4 papers); alopecia (1); colorectal cancer (1); dementia (1); Hearing impairment (1); hypohidrosis (1); liver cancer (1); tooth agenesis (1); tricho-dento-osseous syndrome (1).